AJAP1 (adherens junctions associated protein 1)
Description:
Plays a role in cell adhesion and cell migration.
Synonyms: MOT8; SHREW1; SHREW-1
Tractability: Antibody: UniProt places it where antibodies can reach, with high confidence; its Gene Ontology location is reachable by antibodies, with high confidence; UniProt predicts a signal peptide or a membrane-spanning region.
Gene: Protein-coding gene on chromosome 1 (4,654,609 to 4,792,534, forward strand). Ensembl gene ENSG00000196581.
Subcellular location: Basolateral cell membrane; Apical cell membrane; Cell junction, adherens junction
Gene Ontology:
Molecular function: beta-catenin binding; protein binding; protein-containing complex binding; protein domain specific binding
Biological process: negative regulation of cell-matrix adhesion; negative regulation of wound healing; regulation of polarized epithelial cell differentiation
Cellular component: adherens junction; apical plasma membrane; basolateral plasma membrane; cell surface; cell-cell contact zone; cytoplasmic side of plasma membrane; plasma membrane
Genetic constraint (gnomAD): Loss-of-function variants: 5 observed, 27.99 expected, observed/expected ratio (o/e) 0.18, 90% interval 0.092 to 0.38. The synonymous counts are far from expectation, so gnomAD's model fits this gene poorly and the ratio says little. Missense variants: 575 observed, 517.49 expected, observed/expected ratio (o/e) 1.11, 90% interval 1.04 to 1.19. Synonymous variants: 282 observed, 226.48 expected, observed/expected ratio (o/e) 1.25, 90% interval 1.13 to 1.37.
Homologues: Orthologues: chimpanzee AJAP1 (99% identical), macaque AJAP1 (99% identical), pig AJAP1 (85% identical), dog AJAP1 (84% identical), guinea pig AJAP1 (81% identical), mouse Ajap1 (79% identical), rat Ajap1 (76% identical), tropical clawed frog ajap1 (49% identical), zebrafish ajap1 (39% identical).
Diseases named in the same sentence as AJAP1 in open-access papers:
AJAP1 is named in the same sentence as 41 diseases in open-access papers, as found by Europe PMC text mining. Sharing a sentence is not in itself a finding about the gene and the disease. The quoted sentences say what the papers report.
hepatocellular carcinoma (10 papers, 2016 to 2024). A malignant tumor that arises from hepatocytes. "Adherens turbine-associated protein 1 (AJAP1) is a transmembrane protein in epithelial cell adhesion junctions and has shown tumor inhibition activity in hepatocellular carcinoma, esophageal cancer, and breast cancer." (PMID 36330441, 2022). "AJAP1, a novel tumor suppressor gene, is associated with survival in esophageal squamous cell carcinoma, hepatocellular carcinoma, and glioma." (PMID 28852427, 2017). "Diminished expression of AJAP1 serves as an unfavorable prognostic indicator in hepatocellular carcinoma, glioma, and esophageal cancer." (PMID 38928496, 2024). "Adherens junctions-associated protein 1 (AJAP1 or Shrew-1), was originally found in epithelial cells and confirmed to be implicated in glioma, hepatocellular carcinoma, and esophagus carcinoma." (PMID 35831825, 2022). "In liver cancer, miR-552 promotes the proliferation, migration and EMT of hepatocellular carcinoma cells by inhibiting AJAP1 expression." (PMID 34539882, 2021). "Our goal was to explore the function of miR‐552 and its potential target AJAP1 in hepatocellular carcinoma (HCC) oncogenesis and progression." (PMID 30597727, 2019). "Some studies then verified that AJAP1 was a promising tumor candidate gene in glioma, hepatocellular carcinoma, esophagus carcinoma and oligodendrogliomas." (PMID 31171012, 2019). "The novel molecule of AJs, AJAP1, was found to be a tumor suppressor in glioma, hepatocellular carcinoma, esophagus carcinoma, oligodendrogliomas, and cervical cancer." (PMID 31171012, 2019). "It has been shown that the expression of AJAP1 is dysregulated in various cancer types including glioma, hepatocellular carcinoma (HCC) and esophageal squamous cell carcinoma (ESCC)." (PMID 28483980, 2017). "Our results support previous studies, which indicate a significant correlation between reduced AJAP1 mRNA levels and an increased tumor vascularization in patients with hepatocellular carcinoma." (PMID 28483980, 2017). "More recent evidence indicates that the SHREW-1/AJAP1 gene is also silenced in other tumor types such as gastric, cervical and endometrial cancer, or hepatocellular carcinoma." (PMID 27870635, 2016). "Overexpression of AJAP1 may reduce metastasis of hepatocellular carcinoma." (PMID 36662838, 2023).
breast carcinoma (8 papers, 2017 to 2025). "The study revealed that reduced TET1 levels hindered hydroxymethylation of the AJAP1 (adherens junctions associated protein 1) promoter, thereby activating β-catenin signaling and promoting urinary breast cancer development." (PMID 40520993, 2025). "Taken together, AJAP1-Ezrin+ was a potential risk factor for predicting breast cancer patients with poor prognosis." (PMID 35311087, 2022). "AJAP1 expression was negatively associated with Ezrin expression including the prognosis function for breast cancer patients." (PMID 35311087, 2022). "In our research, we found that AJAP1 expression was negatively linked with Ezrin expression and their combination can predict the prognosis of breast cancer." (PMID 35311087, 2022). "After that, the effect of changing the AJAP1 expression on the cytoskeleton of breast cancer cells was explored." (PMID 35311087, 2022). "Next, the effect of changing the AJAP1 expression on the cytoskeleton of breast cancer cells was explored." (PMID 35311087, 2022). "Next, ROC curves and the area under the curve (AUC) were used to assess the accuracy of AJAP1 and Ezrin expressions as biomarkers for breast cancer diagnosis." (PMID 35311087, 2022). "AJAP1 and Ezrin expressions were detected in 377 cases of breast cancer using immunohistochemistry (IHC) technology." (PMID 35311087, 2022). "This study was set out to investigate the relationship between them and to further explore the mechanism of AJAP1-mediating cytoskeleton in breast cancer progression." (PMID 35311087, 2022). "In the current study, we first investigated the relationship between Ezrin and AJAP1 expression and then evaluated their prognosis accuracy in predicting prognosis of breast cancer patients." (PMID 35311087, 2022). "Ezrin and AJAP1 expressions were detected in 377 samples of breast cancer by immunohistochemistry, and different expression patterns between AJAP1 and Ezrin with clinicopathological parameters were analyzed." (PMID 35311087, 2022). "Results demonstrated that AJAP1 AUC was 0.777 (95% confidence interval was 0.711–0.844, p < 0.0001) in different breast cancer patients and the optimal cutoff value was 0.528." (PMID 35311087, 2022). "Our previous study verified that AJAP1 depletion promoted breast cancer progression by accelerating β-catenin nuclear transaction." (PMID 35311087, 2022). "AJAP1 is a novel protein of adherens junction and has also been explored in 377 samples of breast cancer tissues." (PMID 35311087, 2022). "The stable overexpression of AJAP1 in MCF7 breast cancer cells accelerated cell migration with knockdown decreasing migratory behavior." (PMID 34830797, 2021). "A recent study reported that AJAP1 functions as a negative regulator of WNT signaling through preventing nuclear translocation of β-catenin by anchoring to cell membrane in breast cancer cell." (PMID 32635647, 2020). "Given the inhibition effect of AJAP1 on breast cancer both in vivo and in vitro, new medicine targets need to be developed." (PMID 31171012, 2019). "AJAP1 and β-catenin expressions in breast cancer tissues and cell lines were detected by immunohistochemistry, western blotting and qRT-PCR." (PMID 31171012, 2019). "We reported a novel EGF/EGFR axis that negatively fed back on the AJAP1-mediated β-catenin expression pathway and it accelerated breast cancer progression." (PMID 31171012, 2019). "T47D cells with knocking down of AJAP1 expression and MDA-MB-231 cells with overexpression of AJAP1 were then generated to evaluate the proliferation, migration and invasion of breast cancer by MTT, Transwell, colony-formation and wound-healing assays." (PMID 31171012, 2019). "This study demonstrated that AJAP1 was a putative suppressor in breast cancer and it can interact with β-catenin in the cytoplasm and membrane." (PMID 31171012, 2019).
breast carcinoma (continued). "This study aimed to investigate the function and mechanism of AJAP1-mediated β-catenin activity of breast cancer lines in vitro and in breast cancer patients." (PMID 31171012, 2019). "More importantly, EGFR depletion/AJAP1 knocked down promoted the progression of breast cancer by regulating the activity of β-catenin nuclear transactivation." (PMID 31171012, 2019). "The dataset from Finak (GOBO)and Oncomine showed that AJAP1 was downregulated in the breast cancer tissues compared with the normal tissues." (PMID 31171012, 2019). "Collectively, AJAP1 inhibited breast cancer growth by regulating β-catenin transcriptional activity through suppressing C-myc and CyclinD1 expression both in vivo and in vitro." (PMID 31171012, 2019). "Collectively, EGF/EGFR/AJAP1 axis controled breast cancer tumor progression and metastasis by mediating the β-catenin nuclear transactivation." (PMID 31171012, 2019). "In breast cancer cells, AJAP1 has been shown to accelerate the process of wound closure, while the downregulation of AJAP1 reduces the migratory capacity of cells." (PMID 28483980, 2017). "The influence of AJAP1 on cell migration and invasion has been observed previously in glial-derived tumors and human mammary carcinoma (MCF-7) cells." (PMID 28483980, 2017). "In polarized epithelial cells, AJAP1 localizes and interacts with β-catenin in the E-cadherin-catenin complex and is found in cell-cell contacts in the human mammary gland, the uterus, breast carcinoma cells and in glioblastoma cell lines." (PMID 28483980, 2017). "In breast cancer cells, AJAP1 has been shown to modulate epithelial growth factor (EGF)-dependent E-cadherin internalization, a process that occurs during tissue remodeling and pathological processes such as tumor development." (PMID 28483980, 2017). "AJAP1/Ezrin expression and clinicopathological parameter in patients with breast cancer patients." (PMID 35311087, 2022). "Thus, AJAP1-positive staining was observed in 213 (56.5%) cases of 377 breast cancer samples and Ezrin-positive staining occurred in 165 (43.77%) cases of 377 breast cancer tissue slides." (PMID 35311087, 2022). "Besides, we also demonstrated a new relationship between AJAP1 and Ezrin in mediating the cytoskeleton of breast cancer cells." (PMID 35311087, 2022). "AJAP1 and Ezrin expression with clinicopathological parameters in breast cancer patients." (PMID 35311087, 2022). "AJAP1 depletion might mediate breast cancer malignancy potential through promoting Ezrin expression and cytoskeleton formation." (PMID 35311087, 2022). "More importantly, these results might bring a new insight on the feedback loop of AJAP1 and Ezrin in breast cancer progression." (PMID 35311087, 2022). "However, further studies were needed to analyze the concrete pathway between AJAP1-mediated Ezrin activity in prohibiting breast cancer progression and related clinical therapeutic strategies." (PMID 35311087, 2022). "Collectively, AJAP1 negatively mediated Ezrin expression in breast cancer cell lines." (PMID 35311087, 2022). "Moreover, our report provided the first document to explore the relationship between AJAP1 and Ezrin expression in breast cancer tissue slides and analyzed their expression with clinicopathological parameters." (PMID 35311087, 2022). "This research provided novel findings demonstrating that the combination of the inhibitor of EGFR and the AJAP1 inducer may be beneficial to breast cancer prognosis." (PMID 31171012, 2019). "Likewise, AJAP1 regulated breast cancer tumorigenesis via mediating the β-catenin activity, indicating an effective way to prevent the tumor progression." (PMID 31171012, 2019). "In polarized epithelial cells, AJAP1 localizes and interacts with β-catenin in the E-cadherin-catenin complex and is found in cell-cell contacts in the human mammary gland, the uterus, and breast carcinoma cells." (PMID 30673708, 2019). "In conclusion, AJAP1 was a putative tumor suppressor in breast cancer." (PMID 31171012, 2019).
breast carcinoma (continued). "Furthermore, the function of AJAP1 and β-catenin regulated breast cancer progression was explored both in vivo and in vitro." (PMID 31171012, 2019). "Besides, AJAP1 was a putative tumor suppressor that suppressed the growth, migration, invasion of breast cancer and cell cycle by mediating the nuclear β-catenin activity." (PMID 31171012, 2019). "In summary, these results indicated that AJAP1 expression could be a prognostic marker in the different risks of subgroups of breast cancer patients, while β-catenin didn’t have the same function." (PMID 31171012, 2019). "In this study, the roles of AJAP1 and β-catenin in breast cancer were explored." (PMID 31171012, 2019). "In this work, AJAP1 was mainly located in the cytoplasm and was downregulated in breast cancer." (PMID 31171012, 2019). "However, our study explored and validated that EGFR also can inhibit AJAP1 expression and β-catenin activity in breast cancer cells." (PMID 31171012, 2019). "Overall, these results showed that EGFR and EGF could inhibit the expression of AJAP1 and promot the β-catenin nuclear localization in the breast cancer cell lines." (PMID 31171012, 2019). "Then we explored whether the function of AJAP1 in breast cancer progression relied on mediation of β-catenin expression." (PMID 31171012, 2019). "Besides, the results of AJAP1 and β-catenin expression in 283 cases of breast cancer patients and overall survival further confirmed this theory." (PMID 31171012, 2019). "Furthermore, 283 breast cancer formalin-fixed, paraffin-embedded tumor slides with complete clinicopathological characteristics and follow-up data were utilized to analyze the expression of AJAP1." (PMID 31171012, 2019). "AJAP1 knocked down contributed to breast cancer malignancy through promoting accumulation of aberrant β-catenin nuclear expression, which indicated that increased expression of AJAP1 in higher grades of breast cancer could be beneficial to abrogate the β-catenin driven malignancy." (PMID 31171012, 2019). "AJAP1/EGFR KD group improved the tumor growth and weight, β-catenin nuclear expression and the expressions of C-myc and CyclinD1 compared with the other two groups isolated from the breast cancer cell-inoculated nude mice." (PMID 31171012, 2019). "It was found that AJAP1 had a high negative correlation with β-catenin nuclear expression and was a novel tumor suppressor in breast cancer." (PMID 31171012, 2019).
glioblastoma (8 papers, 2013 to 2024). The most malignant astrocytic tumor (WHO grade IV). "The epigenetic silencing and deletion of AJAP1 on human chromosome 1p36 was correlated with glioblastoma tumors and this loss of expression is due to promoter methylation." (PMID 30673708, 2019). "Pathogenesis and survival rate of tumor diseases such as glioblastoma and esophageal cancer have been associated with altered expression of AJAP1, thereby making it an interesting molecular diagnostic marker in cancer therapy." (PMID 28483980, 2017). "Paradoxically, the overexpression of AJAP1-attenuated glioblastoma cell line adhesion capacity to extracellular matrix components (laminin, collagen IV and fibronectin), with delayed wound-healing closure only observed on fibronectin-coated plates." (PMID 34830797, 2021). "Further, AJAP1 overexpression in glioblastoma cell lines decreases cell migration; our findings in HUVECs are concordant with the studies on glioblastoma." (PMID 28483980, 2017). "AJAP1 has been studied in glioblastoma, which is one of the most common and most malignant primary tumors in the central nervous system associated with poor patient survival rates." (PMID 28483980, 2017). "AJAP1 overexpressing glioblastoma cell lines display a change in the cellular distribution of F-actin and β-tubulin." (PMID 28483980, 2017). "Additionally, previous studies have found AJAP1 to be highly methylated in glioblastoma, neuroglioma, prostate cancer, and endometrial cancer." (PMID 38928496, 2024). "Especially in glioblastoma, AJAP1’s role has been fully explored." (PMID 35311087, 2022). "AJAP1 suppresses cell proliferation, migration and invasion and alters cytoskeletal reorganization in glioblastoma in vitro and in vivo by as yet unknown mechanisms." (PMID 28483980, 2017). "Paradoxically, overexpression of AJAP1 in MCF-7 cells increases cell migration and loss of AJAP1 decreases the migration behavior, whereas in highly invasive glioblastoma tumors and glioblastoma cell lines, AJAP1 expression is lost by methylation of the AJAP1 promotor." (PMID 28483980, 2017). "Interestingly, restoration of AJAP1 gene expression by transfection or demethylating agents decreased tumor cell proliferation and migration in glioblastoma cell lines." (PMID 28514750, 2017). "However, in the glioblastoma context, it has been observed that upon restoration of AJAP1 expression, the cytoskeleton is altered." (PMID 28483980, 2017). "Interestingly, a similar epigenetic signature for AJAP1, ADARB2 and PTPRN2 has been previously reported in glioblastoma." (PMID 28514750, 2017).
glioma (7 papers, 2017 to 2024). A benign or malignant brain and spinal cord tumor that arises from glial cells (astrocytes, oligodendrocytes, ependymal cells). "AJAP1 has been proved as a tumor suppressor in glioma, hepatocellular carcinoma, esophagus carcinoma, oligodendroglioma, and endometrial cancer." (PMID 35311087, 2022). "Previous studies showed that AJAP1 controlled cell cytoskeleton to inhibit the tumor progression of glioma." (PMID 35311087, 2022). "As was demonstrated by Han et al27, AJAP1 overexpression in vitro functioned similarly to in vivo overexpression in glioma cell lines." (PMID 30597727, 2019). "In this context, glioma cells stably overexpressing AJAP1 show a reduced migratory capacity compared to wild-type cells suggesting that AJAP1 actually has an inhibiting effect on cell migration." (PMID 28483980, 2017).
esophageal squamous cell carcinoma (4 papers, 2017 to 2022). Esophageal squamous cell carcinoma (ESCC) is a type of esophageal carcinoma (EC) that can affect any part of the esophagus, but is usually located in the upper or middle third. "Previous research showed that AJAP1 is an independent prognostic factor of squamous cell carcinoma of the esophagus." (PMID 35646092, 2022). "In various tumors, AJAP1 expression is reduced or lost, including hepatocellular and esophageal squamous cell carcinoma, and glial-derived tumors." (PMID 28483980, 2017). "Several evidences concerning the role of AJAP1 as a putative tumor suppressor genes regulated by promoter hypermethylation have been reported in cervical cancer, esophageal squamous cell carcinoma and gastric cancer." (PMID 28514750, 2017).
cervical cancer (3 papers, 2017 to 2022). A primary or metastatic malignant neoplasm involving the cervix. "In general, mRNA expression levels are lower in cervical cancer cells lines than in HaCaT cells, except for SOX17 and MYOD1 in SiHa cells, MGMT in C-33A cells and AJAP1, SOX17 and MYOD1 in HeLa cells." (PMID 34991696, 2022).
oligodendroglioma (3 papers, 2017 to 2019). A well-differentiated (WHO grade II), diffusely infiltrating neuroglial tumor, typically located in the cerebral hemispheres. "Overexpression of AJAP1 in oligodendroglioma cell lines indicates that AJAP1 localizes at the adherens junctions, where it could interact with β-catenin." (PMID 28483980, 2017). "However, in highly invasive oligodendroglioma cells, AJAP1 is epigenetically down-regulated." (PMID 28483980, 2017). "In surgical sections of diffuse astrocytoma, AJAP1 localizes at the cell membrane, whereas in oligodendroglioma sections AJAP1 is not detectable at all." (PMID 28483980, 2017).